CD80 (CD80 molecule)
Diseases named in the same sentence as CD80 in open-access papers (continued):
Sharing a sentence is not in itself a finding about the gene and the disease.
infection (313 papers, 2004 to 2026). The state of being infected such as from the introduction of a foreign agent such as serum, vaccine, antigenic substance or organism. "Chromatin accessibility for pro-inflammatory and infection-associated genes such as Il1b, Il6, Nlrp3, Itgam (Cd11b), CD80, CD14, Fos, and Jun were also increased in infected AMs and IMs (cluster 5)." (PMID 34292313, 2021). "We report here that, in contrast to wild type HSV-1, DCs were susceptible to infection by a recombinant HSV-1 expressing murine CD80 (B7-1) under the LAT promoter." (PMID 24475315, 2014). "The susceptibility of DCs to HSV-CD80 infection was due to binding of viral expressed CD80 to PD-L1." (PMID 24475315, 2014). "Upon EV1-infection, a more pronounced upregulation of CD80 and PDL1 is observed compared to CD86, probably caused by relative high expression of CD86 under unstimulated conditions (mock) that reaches a plateau-phase upon stimulation (EV1)." (PMID 23638101, 2013). "T. annulata- transformed cells were shown to express high levels of CD40 and CD80 and were susceptible to infection with BHV-1, vaccinia and canarypox viruses." (PMID 22182243, 2011). "For example, while the levels of CD40 and CD80 (data not shown) in MoDCs also increased, it was rather surprising to observe that infection of Mφs with either Bp-844 or Bt-UE5 actually caused a reduction in the levels of CD80 and CD11b." (PMID 19397822, 2009). "F-MLV infection caused up-regulation of CD80 on all three major splenic DC subsets in heterozygous mice." (PMID 19214214, 2009). "Over the course of infection, genome amplification correlated with increases in expression of two of the six bat host genes tested including CD80, a DC activation marker associated with T-cell priming, and CCL3, a potent chemokine produced by APCs upon stimulation with LPS." (PMID 31681302, 2019). "MHC class I (MHC‐I, HLA‐A/B/C) expression remained largely unaltered, while CD80 or CD86 costimulatory molecules were undetectable at baseline or upon infection." (PMID 39535369, 2025). "On day 3 post-infection, the oseltamivir group exhibited a significant decrease in CD80 expression (P < 0.05)." (PMID 40959060, 2025). "Simultaneously, NH/P68 infection induces the downregulation of CD80/86 costimulatory molecules on mature moDCs while promoting the upregulation of MHC class II molecules." (PMID 40817451, 2025). "This co-culture revealed that infection with H. pylori at the apical side of the mucosoid robustly activates DCs cultured at the basal side, as indicated by increased CD80, CD86, and PD-L1 expression." (PMID 39288239, 2024). "Mock infected RAW 264.7 cells exhibited moderate basal CD80 expression, however, upon infection there was a distinct shift in intensity that is indicative of M1 polarization." (PMID 39405316, 2024). "The mock infected group did exhibit a sizable amount of residual CD80 staining, however, there was a distinct shift in intensity upon infection." (PMID 39405316, 2024). "According to the cellular communication heatmap and network diagram, the CD80 signaling pathway related to T-cell activation was increased at 6 w after infection." (PMID 39590301, 2024). "The CD80 signaling pathway related to T-cell activation was increased at 6 w after infection, and increased expression of its receptor CD28 on the surfaces of CD4+ and CD8+ T-cells was confirmed by flow cytometry, suggesting an increase in their activation." (PMID 39590301, 2024). "In the hemocyte population, CD80 cell positivity is weak and seems weakly influenced by the presence of the infection induced by S. aureus." (PMID 38191588, 2024). "NanoS100–SwIAV vaccine upon the SwIAV-H1N1-OH7 and H1N1 pandemic virus challenge infection stimulated the population of CXCL10+CD80/86+-activated monocytes in the draining TBLN and in the systemic compartment." (PMID 38006039, 2023).
infection (continued). "In order to assess the activation status of these infected cells ex vivo, we first examined the expression of the activation markers CD40 and CD80 on T. cruzi-infected cells from the infection site." (PMID 36695605, 2023). "Upon infections in vivo we found trogocytosis of CD80 and CD86 to predominantly occur in lymphatic organs, suggesting that the fate-separating effects of CD28 and CTLA4 on trogocytosed ligands regulate T cell behavior at these sites." (PMID 36309492, 2022). "Significant upregulation of CD80 for all JD infection status groups was observed following infection of MDM cultures with MAP (P < 0.001)." (PMID 36275033, 2022). "Following Lt-wt infection, DCs expressed significantly higher levels of CD80/CD83 and HLA-DR II compared to MED treatment." (PMID 35632559, 2022). "It has been shown that in vitro T. cruzi-infection of monocytes from indeterminate patients led to a decreased expression of HLA-DR, but increased expression of CD80." (PMID 34336723, 2021). "More CD3+ γδT+ cells were expressing CD80, CD11b, and PD-1 post-infection (p < 0.05), while less CD3+ γδT+ cells were expressing CD34, CD127, and CD62L in the infected mice (p < 0.05)." (PMID 33588839, 2021). "By 5 weeks post-SIV TypP infants exhibited significantly higher CD80+ B cells than RP infants and this trend continued through 12 weeks post-infection, with TypP infants having on average 8.4-fold higher levels of circulating B cells expressing CD80." (PMID 33961680, 2021). "Another key observation is that after 10 months post-infection, the frequency and absolute counts of activated B cells (CD80+/CD86+) were higher in convalescent individuals." (PMID 35069575, 2021). "The percentages of CD69, ICOS, or CD80-expressing B cells increased in infected mice during the course of infection (p < 0.01)." (PMID 33588839, 2021). "While some expression patterns remained elevated during infection, by day 5 there was increased Il-12a, Il-12b, Il-6, Cd80, and Cxcl11 expression that corresponded with elevated Il-15 levels in young adult H1N1 and H3N2 infected lung." (PMID 34829979, 2021). "Expression of CD80 mRNA was numerically greater among all other surface molecules in both groups at 6 h post-infection." (PMID 34446765, 2021). "Infection with ΔtcpAh mutant A. hydrophila dramatically upregulated CD80/86 expression in fish, and this outcome was attenuated by supplementing CP-TcpAh protein." (PMID 34305858, 2021). "At 1 and 2 weeks pi, B cells expressing the CD80 activation marker were more strongly induced in CD3ko-Nef than in WT SIVmac239 infection (right)." (PMID 32075764, 2020). "As infection persisted, we observed an increase in the cytokine TNFα; a decrease in the cytokine IL-6; an increase in T-cell priming co-receptors CD80/86, and MHCII; and a decrease in CD103 and IL-10." (PMID 32635236, 2020). "Infection resulted in immune-cell activation, with upregulation of cell surface activation markers (e.g., CD80, PD-L1, HLA-DR) and secretion of proinflammatory cytokines (IFN-α2a, IL-6, IL-8, TNF-α)." (PMID 32088771, 2020). "As observed in vaccinees, YF-17D infection of PBMCs also induced upregulation of activation markers on various immune cells, including CD80 and CD86 on myeloid DCs (mDCs) and CD54 and CD69 on monocytes." (PMID 31285858, 2019). "The expression of the analyzed surface markers differed between the DC subsets upon infection, with the highest expression of CD80 and PD-L2 on the CD4+ DC subset." (PMID 31134074, 2019). "During the infection of JD(–) macrophages, CD80 expression was already DE at 1 hpi and progressively increased during the 24-h period." (PMID 31969876, 2019). "Recent studies have reported new evidence on the pathophysiology of infection related proteinuria, including the role of B7-1(CD80) protein, expressed on both circulating leucocytes as well as on glomerular epithelial cells (podocytes)." (PMID 30175088, 2018).
infection (continued). "MSP121-specific AMB sorted during chronic P. chabaudi infection, and MSP121-specific Bmem sorted after resolution of the infection shared the expression of a series of mouse memory markers, including Cd80, Fcrl5, Nt5e (CD73), and Cd86." (PMID 30387712, 2018). "All NPs-treated HSV-2 retained CD86 expression and down-regulated CD80 expression in comparison to infection with live HSV-2." (PMID 29872440, 2018). "With the exception of CD80 expression, infection by L. braziliensis leads to a higher intensity of expression of all analyzed molecules when compared with L. infantum strains in monocytes." (PMID 29358935, 2017). "Although the proportion of CD80-positive CD11c+ DCs was similar in all treatment groups, ΔN146 infection and LPS stimulated higher surface expression of CD80 molecules than mock infection." (PMID 28150813, 2017). "In fresh whole blood, less than 1% of pDC expressed CD86, CD40 or CD80 before infection or at peak parasitaemia." (PMID 28572564, 2017). "Infection of the human monocytic cell line U937 with primary isolates of an Indian HIV-1 subtype C induced the downregulation of CD80 and CD86." (PMID 29023371, 2017). "CD80 is normally expressed on BM-derived cells, and further upregulation is seen in cases of infection and inflammation." (PMID 27125280, 2016). "At 40 hours post infection, we examined the expression levels of markers associated with DC maturation including CD86, CD80 and CD54." (PMID 27930745, 2016). "Although pDC CD80 levels were unaltered on day 5 post infection in MLN and PLN of RRV-infected NOD.IFNAR1−/− mice, pDC expression of MHC I was elevated in MLN and PLN." (PMID 27405244, 2016). "Expression of MHC class II (p < 0.001), CD40 (p = 0.032) and CD80 (p = 0.044) were significantly enhanced following infection of DCs with BCG compared with uninfected DCs." (PMID 27530534, 2016). "Regardless, additional studies are needed to understand how CD80 expression impacts RORγt+ ILC function during infection." (PMID 26010337, 2015). "ALE (200 mg/kg bw) elevated CD80 and CD86 expression profile to 55.5% (P < 0.001) and 28.8% (P < 0.001), respectively in comparison with infection control (CD80 = 34.9%, CD86 = 13%)." (PMID 25884649, 2015). "EPO (which is elevated during infection with Salmonella) was shown to increase the numbers of splenic macrophages, upregulate the expression of F4/80, CD11b, and CD80 cell markers, and enhance their pro-inflammatory and phagocytic activity." (PMID 26068006, 2015). "Propofol exposure was observed to disproportionally affect the frequency of F4/80+CD80+MHC-II+ mononuclear phagocytes present at sites of infection, along with evidence of a trend in TipDC reduction." (PMID 26381144, 2015). "Taken together, our results show that infection of human cells with the Col cl1.7 leads to a higher expression of CD80 and CD86, as well as of IL-17, favoring monocyte activation." (PMID 26147698, 2015). "Propofol exposure thus reduces total innate immune effector cells at sites of infection with an increased proportional reduction in F4/80+CD80+MHC-II+ mononuclear phagocytes and a trend towards reduced TipDC populations." (PMID 26381144, 2015). "Propofol did not reduce the recruitment of CCR2+Ly-6C+ mononuclear phagocytes to the spleen following bacterial infection or alter the number of differentiated F4/80+CD80+MHC-II+ mononuclear phagocytes at 24 hours post-infection." (PMID 26381144, 2015). "Our results suggested that viral CD80 binds to PD-L1 on the surface of DCs and facilitates cell infection and lysis." (PMID 24475315, 2014). "Although, there was no HSV-2-driven increase in the expression of α4β7 on all the APCs in the tissue, we found that the frequency of α4β7high CD80+ APCs 3 days after infection was higher in the HSV-2 infected tissues than in the controls." (PMID 25521298, 2014).
infection (continued). "CD86 showed a pattern of significantly increasing expression with age at infection, and CD80 showed lower expression in mice infected at or under two weeks old than during adult infection." (PMID 24550729, 2014). "CD80/CD86 antibodies had the largest effect on CD8+ T cell responses when administered two days post-infection." (PMID 24550729, 2014). "Both BDCA-1+ and BDCA-3+ mDCs were susceptible to infection with RSV and demonstrated enhanced expression of CD86, and the inhibitory costimulatory molecules CD80 and PD-L1." (PMID 23829893, 2013). "Remarkably, infection with Seui strain induced higher TNFα, CD80 and IL-10 expression than pN3 treated cells." (PMID 24070317, 2013). "At day 2 post-infection, we noted 18–19% increase on the percentage of CD80 and CD86 expression on WNV H8912-infected BMDCs when compared to WNV NY99-infected cells respectively (P<0.01)." (PMID 23785537, 2013). "Before infection, the immature DC phenotype (CD1a +, HLA-DR +, CD80 −, CD86 −, CD14 −, CD83−) was verified by flow cytometry (Figure A1)." (PMID 23970881, 2013). "By 24 h, the infection induced significant recruitment and activation (enhanced expression of CD80, CD86 and MHC-II) of macrophages into bronchoalveolar spaces." (PMID 22768201, 2012). "In a previous study it was shown that infection of dendritic cells with strain 3267 resulted in an increase of SLA-II+/CD80/86- and SLA-II-/CD8086+ cells while strain 3262 induced a decrease in the proportion of SLA-II+/CD80/86+ cells." (PMID 22515169, 2012). "During the acute SIVmac239 infection, the percentage of CD80+ CD1c+ mDCs increased from 1.36±0.24% to the peak at day 10 (15.25±8.61%) and sustained a high percentage till day 19 (3.93±0.48%), and showed a significant increase at day 19 (P = 0.011)." (PMID 22174949, 2011). "In comparison with the CD8− DC isolated from BCG infected mice iCD8− DC, the CD8+ DC isolated from the mice with the same infection iCD8+ DC expressed higher CD80 (65.66% vs 17.43%), CD86 (57.43% vs 30%) and CD40 (44% vs 35%) molecules." (PMID 20174628, 2010). "The DC activation statusafter infection was evaluated by assessing the expression of the co-stimulatory molecules CD80 and CD86, as well as by their capacity to present MHC class I and II restricted epitopes to OVA-specific CD8+ or CD4+ T cells, respectively." (PMID 20628596, 2010). "To determine if F-MLV causes activation of specific DC subsets during infection, we infected C57BL/6 mice with F-MLV and examined the expression of CD80 and CD86 on all three splenic DC subsets at different times post-infection." (PMID 19214214, 2009). "After infection, the percentages of CD80 and CD86 memory B-cells had decreased by factors of 2.2 and 2 by D14 p.i., by factors of 1.6 and 2.3 by D21 p.i. and by factors of 3 and 3.5, respectively, by D28 p.i.." (PMID 19543531, 2009). "The results were consistent with our earlier findings; CD80 expression was reduced from 41% to 35% after LV-PLAP infection, while CD86 expression was reduced from 61% to 49%." (PMID 15518595, 2004). "The infection-mediated decrease in CD80/86 expression on mature moDCs suggests that ASFV may impair naive T cell activation through reduced costimulatory molecule expression." (PMID 40817451, 2025). "Although infection induced CD80, CD83, CD86, and HLA class II expression on the surface of DCs, the activation of CD4+ T cells was impaired, which is consistent with findings in RSV-infected murine DCs, where the formation of immunological synapses was impaired." (PMID 41280933, 2025). "The resulting activation state, which was maintained up to 96 h post-infection, as characterized by detectable levels of viral E and NS1 proteins, as well as by CD11b, CD11c, CD80, and CD86, which are proteins associated with a pro-adherent phenotype and pro-inflammatory state." (PMID 38247836, 2024). "Therefore, we compared WT and CD80-/- mice after infection with HSV-CD80 and its parental control dLAT2903 virus." (PMID 39339855, 2024).
infection (continued). "Previous work has demonstrated that cd86 and cd80 are upregulated at the transcriptional level to a greater extent during MP-12 infection of microglia versus ZH501 at 4 h post infection, which may be a downstream effect of lower-type I IFN induction by ZH501." (PMID 38392897, 2024). "However, high levels of CD80 were noted at 12 h after infection, which subsequently decreased by 96 h." (PMID 38012553, 2023). "The expression levels of the M1-like activation markers iNOS, CD80 and CD86 were much higher in SEPT2-deficient PMs upon VSV infection at various time points post-infection and with different multiplicities of infection (MOI)." (PMID 37978190, 2023). "Interestingly, we observed that the enhanced CD80+ CD86+ macrophages in colon tissues derived from mice with translocated infection were in line with the lower levels of secretion of TNF-α." (PMID 36445086, 2022). "Importantly, more CD80+ CD86+ macrophages existed in colon tissues harvested from CRKP-colonized mice with translocated infection." (PMID 36445086, 2022). "Nevertheless, the cDC2 subset was recruited at higher numbers to ICAM-1/2-/- LNs following PR8 infection, and were hyperactivated, as evident by their significantly elevated levels of the major co-stimulatory molecules CD80 and CD86, as well as elevated IL-6 production." (PMID 36895258, 2022). "Importantly, B7-H4−/− infection further regulated the expression of molecules (CD80, CD86, and MHC-II or HLA-DR), enzyme IDO, and cytokines (IL-10 and IL-12) in dDCs." (PMID 35505420, 2022). "We could show that FM+ cells persist weeks after clearance of the primary infection mainly as CD80+CD73+PD-L2+ memory B cells." (PMID 36505408, 2022). "Interestingly, exosomes secreted by microglia during TMEV infection had increased levels of co-stimulatory molecules, CD80, CD86, CD40, on the surface compared to exosomes secreted by microglia during mock infection." (PMID 34485270, 2021). "Similarly, expression of MHC class I molecules was significantly reduced, but the expression level of CD80 was enhanced in the inguinal lymph nodes of LCN2−/− mice after intravenous infection with Mtb for 30 days." (PMID 34563261, 2021). "However, contrasting reports also showed that Th2 cell responses can develop independently of CD80/86-derived signals during infection with N. brasiliensis and T. muris, suggesting that there is a CD80/86-independent pathway for Th2 cell development." (PMID 33983946, 2021). "Thus, infection of mice with KOS-ICP22Δ40 virus resulted in significantly more CD11c+CD80+ expression in the corneas of infected mice than in mice infected with WT KOS virus (P < 0.05)." (PMID 34287036, 2021). "More γδT cells were expressing CD80, CD11b and PD-1 post-infection (p < 0.05)." (PMID 33588839, 2021). "Overall, CD80 was upregulated upon LOAd703 infection, whereas CD86 expression was rather stable." (PMID 33666760, 2021). "Interestingly, acute infection resulted in a reprograming of Kupffer cells to a pro-inflammatory state (CD80+CD206−) that returned to a baseline phenotype 3–4 weeks post-infection." (PMID 33376758, 2021). "Our results showed that MHC II and CD80 expression on γδ T cells was significantly increased in response to infection (P < 0.05), suggesting that the γδ T cells might be presented as APCs, which mediate the immune response in the lung of infected mice." (PMID 32582168, 2020). "Burn injuries are highly susceptible to infection and in a human ex vivo burn model, thermal injury induced LC and DC emigration from the skin, with upregulation of MHC II and costimulatory molecules such as CD80, CD86 and CD40." (PMID 30696002, 2019). "Additionally, RHΔrop16 strain infection significantly promoted M1 macrophage phenotypes of CD80 and CD86, and decreased CD206 expression of M2 macrophages, with upregulation of the iNOS and downregulation of the Arg-1 expression in placental homogenates." (PMID 32082272, 2019).